TNF (tumor necrosis factor)
Diseases named in the same sentence as TNF in open-access papers (continued):
Sharing a sentence is not in itself a finding about the gene and the disease.
Obesity (continued). "More recently, the long-term assessment of anti-TNF-α inhibitor treatment to subjects diagnosed with metabolic syndrome has been shown to improve fasting blood glucose and to increase adiponectin levels, confirming a role for TNF-α in obesity-related insulin resistance in humans." (PMID 24455420, 2013). "In summary, a common inflammatory pathway in both, obesity and asthma, is orchestrated by TNF." (PMID 24454412, 2013). "Moreover, tumor necrosis factor (TNF)-α and interleukin (IL)-6, both of which are major proinflammatory cytokines, play a critical role in obesity-related steatohepatitis and subsequent liver tumorigenesis." (PMID 25674420, 2013). "Resistin and the proinflammatory cytokines, such as TNF-α, IL-6, and IL-1β, produced by adipocytes, and macrophages, are considered to be important modulators of chronic inflammation contributing to the development of obesity and atherosclerosis." (PMID 23484124, 2013). "Additionally, we discuss a working biological model on the onset of destructive periodontal disease in individuals with obesity or metabolic syndrome based on elevated levels of tumor necrosis factor-α (TNF-α) and interleukin 6 (IL-6) in these conditions." (PMID 24068858, 2013). "In addition, they also noted an increasing trend with other pro-inflammatory markers like TNF-α and IL-6 with overweight/obesity." (PMID 24025484, 2013). "In detail, inflammatory cytokines that are elevated during the course of obesity such as TNF-α activate upstream kinases of JNK that phosphorylate JNK-1 and JNK-2 at specific Thr and Tyr residues resulting in JNK activation that can be monitored by several means." (PMID 23349837, 2013). "In conditions of hyperleptinemia, as occurs in obesity, an expansion of the Th1 cells in the adipose tissue and an increase in pro-inflammatory cytokine secretion (as TNF-α, IL6 and IL12) have been described together with an increase of CD8+ T cells, macrophages and mast cells." (PMID 24084730, 2013). "Other studies in obesity and diabetes men, TNFα concentrations were unchanged or decreased." (PMID 24325472, 2013). "Specifically, we suggest that elevated levels of tumor necrosis factor-α (TNF-α) or interleukin 6 (IL-6)—both adipokines and known risk factors for destructive periodontal disease—in obesity and metabolic syndrome contribute to the onset and development of destructive periodontal disease." (PMID 24068858, 2013). "Initial studies reported the accumulation of macrophages within adipose tissue and the subsequent liberation of proinflammatory cytokines such as interleukin-1 (IL-1), IL-6, and tumor necrosis factor alpha (TNF-α), which contribute to obesity-associated insulin resistance." (PMID 23562076, 2013). "TNF-α, which is correlated with insulin resistance in obesity, could also play similar roles in GDM and preeclampsia as well." (PMID 23691290, 2013). "Our study provides the first evidence of the role of miR-181a in adipocyte differentiation by regulation of TNF-α, which may became a new therapeutic target for anti-obesity drugs." (PMID 24098322, 2013). "Obesity is recognized as being associated with a chronic, low-grade, inflammation, with altered levels of several circulating factors such as C-reactive protein (CRP), tumor necrosis factor α (TNF-α), and interleukin-6 (IL-6)." (PMID 23409006, 2013). "Indeed, inhibition or deletion of TNFα signaling dramatically improves insulin resistance in rodent models of obesity." (PMID 24358263, 2013). "TNF-α and resistin, adipocytokines, are known to be elevated in obesity." (PMID 24049664, 2013). "In addition, TNF signaling is believed playing an important role in obesity since TNFα mRNA or protein was found overexpressed in obese subjects in both experimental and epidemiological studies." (PMID 24094242, 2013).
Obesity (continued). "Obesity is considered as an inflammatory status, because proinflammatory molecules, expressed by adipose tissue such as leptin, TNF-α, IL-6, TGF- β1, adiponectin and C-reactive protein, are increased in obese subjects, especially in females (mainly C-reactive protein and leptin)." (PMID 24028436, 2013). "TNF-α was also reported to induce insulin resistance in both diabetes and obesity." (PMID 24068858, 2013). "TNF-α levels are systemically elevated in both obesity and metabolic syndrome." (PMID 24068858, 2013). "It is conceivable that local and systemic expression of NOV could be related to TNF-α expression because this cytokine is locally increased in obesity and mediates the induction of obesity-related factors such as TGF-β, PAI-1 and CCL-2." (PMID 23785511, 2013). "The results showed that adipocyte TNF-α mRNA level was much higher in the WT chimeras than in the HO-1+/− chimeras, supporting the close link between increased macrophage infiltration and adipocyte inflammation during obesity." (PMID 22761690, 2012). "TNF-α is an important mediators of the inflammatory response in obesity and is highly expressed in infiltrating macrophages and adipocytes,which may also play a role in AHR." (PMID 23056561, 2012). "The increased production of TNF-α has been related to the pathogenesis of various diseases, including rheumatoid arthritis, Crohn's disease, atherosclerosis psoriasis, sepsis, diabetes mellitus, and obesity." (PMID 22462002, 2012). "Obesity results in a proinflammatory state starting in the metabolic cells (adipocyte, hepatocyte, or myocyte) and also recruiting immune cells with the consequent release of inflammatory cytokines (TNF-α, IL-6, adiponectin, etc.)." (PMID 22523672, 2012). "Linear and logistic regression and dose-response curves were used to evaluate relations of tCys with obesity, insulin resistance and inflammatory markers including interleukin-6 (IL-6), tumor necrosis factor-alpha (TNF-α), monocyte chemoattractant protein-1 (MCP-1) and C-reactive protein (CRP)." (PMID 22984471, 2012). "Furthermore, obesity and diabetes compromise the inflammatory system with altered expression of tumour necrosis factor alpha (TNFα) occurring in adipose and muscle tissue of obese humans." (PMID 23125848, 2012). "In the setting of obesity, the ability of the adipose tissue to produce antiinflammatory mediators such as adiponectin decreases, whereas proinflammatory cytokines such as IL-6, TNF-α, and acute phase reactants, and other innate immune mediators increase." (PMID 22509382, 2012). "Cytokines, such as IL-6 and TNF-α, are increased in obesity and correlate with insulin resistance." (PMID 22518191, 2012). "Our primary hypothesis was that the possible beneficial effects of anti-TNFα on IR would be limited by the presence of obesity." (PMID 22765047, 2012). "TNF is a proinflammatory cytokine that links obesity with IR." (PMID 22451839, 2012). "We hypothesize that these factors (FFAs, TNF-α, and resistin) and drug (rosiglitazone) may have a potential regulatory mechanism in obesity through the regulation of LYRM1 mRNA expression, thereby affecting insulin sensitivity." (PMID 22110480, 2012). "The role of TNFα in diet-induced obesity may depend on the TNF receptors activated with TNF receptor 1 being deleterious and TNF receptor 2 being cardioprotective." (PMID 23125848, 2012). "Adipose tissue is an important source of TNF-α, a major proinflammatory factor in obesity." (PMID 22778500, 2012). "In the early stage of HF-diet–induced obesity, inflammation is increased because of inflammatory cell infiltration, and circulating cytokines such as TNF-α and IL-6 are elevated; the latter further activates inflammatory signaling in the liver, which in turn, promotes hepatic lipid accumulation." (PMID 22720061, 2012).
Obesity (continued). "In particular, TLR2 and TLR4 are highly expressed in macrophages and adipose tissue and can be activated by (saturated and oxidatively modified) fatty acids, elevated during obesity, resulting in NFκB-dependent differentiation with enhanced secretion of pro-inflammatory cytokines (e.g. TNFα)." (PMID 22272346, 2012). "Aside from this, obesity can perpetuate both systemic and pulmonary inflammation, since excessive adipose tissue is able to produce various proinflammatory cytokines including interleukin-6 (IL-6) and tumor necrosis factor alpha (TNF-α)." (PMID 23101436, 2012). "It was also suggested that the normalization of adiponectin and its receptors together with TNF- α may result in the amelioration of obesity in insulin resistant obese animals." (PMID 23056223, 2012). "Adipose tissue insulin resistance may occur in obesity in part through the infiltration of macrophages which release pro inflammatory cytokines such as TNFα, IL-6 and IL1β." (PMID 22363403, 2012). "To test this hypothesis, we characterized muscle SOCS3 expression in response to metabolic challenges known to be associated with insulin and/or leptin resistance such as high-fat diet feeding, genetic obesity, lipid infusion, and TNFα injection." (PMID 23115649, 2012). "Genotyping at the TNF-α and GNB3 loci represents an ideal tool for preventive medicine, in that individuals at risk of obesity and AMI can be identified early and their genetic predisposition could be counteracted through changes in lifestyle." (PMID 22408428, 2012). "Another pro-inflammatory cytokine is TNF-alpha, a link between obesity, inflammation and diabetes." (PMID 22848362, 2012). "TNF−/− mice were used to investigate the role of TNFα in obesity." (PMID 23125848, 2012). "It has also been suggested that, as TNF-α can trigger IL-6 release, increased systemic IL-6 levels may reflect enhanced adipose tissue production of TNF-α, the actual driver behind obesity-related insulin resistance." (PMID 22615828, 2012). "Our in vitro experimental data indicate that SBM may be a potent modulator of obesity by repressing the PPARγ-regulated adipogenesis pathway and augmenting the TNFα-induced lipolytic and apoptotic pathway." (PMID 22292054, 2012). "TNF-α is overproduced in the WAT of several animal models of obesity." (PMID 21810260, 2011). "Obesity may increase bone resorption through upregulating proinflammatory cytokines such as IL-6 and TNF-α." (PMID 21676245, 2011). "Even thought that IL-6 is closely associated with TNF-α in exercise, in the present work we chose CRPhs as marker of chronic low-grade inflammation, because CRP is positively correlated with obesity, insulin resistance and has been shown to better predict CVD than other cytokines." (PMID 22174491, 2011). "The increase in obesity-associated OS is probably due to the presence of excessive adipose tissue itself, because adipocytes and preadipocytes have been identified as a source of proinflammatory cytokines, including TNF-α, IL-1, and IL-6; thus, obesity is considered a state of chronic inflammation." (PMID 21686173, 2011). "We measured TNF-α, because is the first molecular link between obesity and T2DM." (PMID 22174491, 2011). "Obesity promotes insulin resistance by resulting in a state of chronic inflammation that involves production of proinflammatory cytokines (TNF-α, IL-6), an increase in the number of macrophages, and activation of a complex cascade of signaling events in muscle, fat and liver tissues." (PMID 21738773, 2011). "Moreover, the infiltration of macrophages in adipose tissue during obesity contributes to increased TNFα production." (PMID 21410966, 2011). "Furthermore, in ovariectomized rats, Boiogito showed an anti-obesity effect, and partial involvement of TNFα was suggested as the mechanism of action." (PMID 19208721, 2011). "TNFα has been proposed to be a key compound of the obesity-diabetes link." (PMID 21826222, 2011).
Obesity (continued). "TNFα is considered a molecule that links inflammation to obesity." (PMID 21410966, 2011). "Indeed, biomarkers of inflammation such as leucocyte count, tumor necrosis factor α (TNFα), interleukin-6 (IL-6) and C-reactive protein are increased in obesity and predict the development of T2D." (PMID 21826222, 2011). "A number of these substances, notably tumor necrosis factor (TNF) alpha and plasminogen activator inhibitor type 1, suggest that obesity is essentially an inflammatory disease, where excess adipose tissue induces macrophage production and activates the immune system without a legitimate pathogen." (PMID 21711516, 2011). "The down-regulation of LPL in the adipose tissues, muscles and kidney under study may be due to inflammatory mediators such as tumour necrosis factor-alpha (TNF-α) which are found to be elevated in obesity and insulin resistant states." (PMID 20670429, 2010). "Systemic inflammation is markedly evident in a number of human and mouse models of obesity, as determined by increased plasma levels of inflammatory cytokines such as tumor necrosis factor-α (TNF-α), interleukin-6 (IL-6), and monocyte chemoattractant protein-1 (MCP-1)." (PMID 20508825, 2010). "The production of IL-6 and TNF-α is increased in adipose tissue of obese individuals, and adipose tissue inflammation is considered to represent an important pathogenetic factor in the development of obesity-related complications such as insulin resistance." (PMID 21197447, 2010). "Strikingly, this obesity-induced increase in TNF-α was completely blunted in IRΔmyel-mice." (PMID 20463885, 2010). "Tumor necrosis factor-α (TNF-α) is also elevated in obesity and may contribute to many aspects of adipose tissue biology including development of insulin resistance and abnormalities in lipid metabolism." (PMID 19709445, 2009). "Interestingly, obesity and type 2 diabetes are also associated with increased expression of TLR2, and obesity induces the expression of a subset of adipocytes that over express both TLR2 and TNFα." (PMID 19348674, 2009). "WRN polymorphisms may also have relevant clinical significance for "normal states" such as stress, obesity, aging or acute inflammation, because they are characterized by high levels of insulin, TNFα, TGFβ." (PMID 18312663, 2008). "In obesity, the white adipose tissue is characterized by an increased production and secretion of a wide range of inflammatory molecules including TNF-α, which may have local effects on white adipose tissue physiology but also systemic effects on other organs." (PMID 19506720, 2008). "One condition already mentioned in which TNF-α is produced and secreted into the blood is obesity." (PMID 19506720, 2008). "Most of them are overproduced during obesity, including leptin, TNF-α, IL-6 and resistin." (PMID 19506720, 2008). "The existence of possible genetic, biological and physical mechanisms (like gastroesophageal reflux) or chemical mechanisms (inflammatory substances like tumor necrosis factor alpha, leptin or adiponectin) that are common to asthma and obesity has been observed." (PMID 19099163, 2008). "Plasma C-reactive protein (CRP), tumor necrosis factor-α (TNF-α), and interleukin-6 (IL-6), markers of inflammation, levels are elevated in subjects with obesity, insulin resistance, essential hypertension, type 2 diabetes, and CHD, suggesting that low-grade systemic inflammation occurs in them." (PMID 18348729, 2008). "Recently it was also shown that TNFα down regulates eNOS expression in metabolically active tissues which might sustain obesity." (PMID 18320034, 2008). "Over the last decade discoveries in the metabolism field, starting with the association of increased tumor necrosis factor alpha (TNF-α) and other inflammatory cytokines in obesity, have demonstrated the strong inflammatory underpinnings of obesity and associated metabolic diseases." (PMID 18773087, 2008).
Obesity (continued). "Plasma levels of C-reactive protein (CRP), tumor necrosis factor-α (TNF-α), and interleukin-6 (IL-6), markers of inflammation are elevated in subjects with obesity, insulin resistance, essential hypertension, type 2 diabetes, and CHD both before and after the onset of these diseases." (PMID 18078524, 2007). "Plasma levels of inflammatory markers such as CRP, TNF-α, and IL-6 are elevated in obesity, insulin resistance, essential hypertension, type 2 diabetes, CHD, and metabolic syndrome X, suggesting that all these disorders are associated with low-grade systemic inflammation." (PMID 18078524, 2007). "Our findings provide further evidence that TNFα system might be involved in the pathogenesis of metabolic syndrome even before the onset of obesity and indicate that its metabolic actions may extend beyond inducing insulin resistance." (PMID 16803616, 2006). "Indeed, obesity induces increased expression of TNF-α and NFκB, leading to down-regulation of insulin receptor and decreasing expression of GLUT4." (PMID 17107852, 2006). "However, data about plasma TNFα receptors as determinants of total and LDL-cholesterol levels and about impact of obesity on the relationships between TNFα system and plasma lipids remain controversial." (PMID 16803616, 2006). "Furthermore, the role of TNF-α in the development of insulin resistance and type 2 diabetes, particularly in the case of obesity-induced diabetes, is now becoming well recognized." (PMID 17107852, 2006). "Changes in TNF-α may be more consistent when there is a predominant genetic basis to the obesity where the level of obesity is usually more extreme." (PMID 15813957, 2005). "It is also probable that this discrepancy may highlight species differences, but it could also indicate that genetic obesity and diet-induced obesity impact differently on the regulation of TNF-α levels." (PMID 15813957, 2005). "Alteration in TNF-α may be tissue specific as shown by a recent study that proposes macrophage-related inflammatory activities in adipose tissue play a role in obesity-related insulin resistance." (PMID 15813957, 2005). "TNF-α, formerly known as cachexin, has been studied in both animal models and human obesity." (PMID 15813957, 2005). "Obesity transforms adipose tissue into a pro-inflammatory endocrine organ, where hypertrophic adipocytes release adipokines such as leptin alongside cytokines including TNF-α and IL-6, potentially contributing to macrophage polarization toward an M1 phenotype and activating NF-κB signaling pathways." (PMID 42188056, 2026). "Chronic low-grade inflammation and upregulation of pro-inflammatory cytokines (e.g., IL-6, TNF-α) in the comorbidity of hypertension and insulin resistance amplify the glomerular and interstitial inflammatory injury triggered by dysglycemia, dyslipidemia, and obesity." (PMID 41601932, 2026). "However, in obesity and under metabolic stress, mesenteric adipose tissue undergoes immune remodelling marked by macrophage polarization, Th1/Th17 differentiation, and fibroblast reprogramming driven by TNFα, IL-6, and TGF-β1." (PMID 42307033, 2026). "Overweight and obesity increased adiposity may enhance a proinflammatory microenvironment through increased production of adipokines such as leptin, visfatin, and resistin, which have been linked to elevated CRP, TNF-α, and IL-6 levels." (PMID 41517610, 2026). "Additionally, the inflammatory markers (TNF-α and leptin) were elevated in cases with obesity." (PMID 41334630, 2025). "Levels of other adipokines, including nerve growth factor (NGF), interleukins, and TNF-α have also been reported to correlate with OAB, suggesting contributions of additional molecular mechanisms to LUTS pathogenesis in association with obesity/metabolic syndrome." (PMID 39989457, 2025).